ACD (ACD shelterin complex subunit and telomerase recruitment factor)
Description:
Component of the shelterin complex (telosome) that is involved in the regulation of telomere length and protection. Shelterin associates with arrays of double-stranded TTAGGG repeats added by telomerase and protects chromosome ends. Without its protective activity, telomeres are no longer hidden from the DNA damage surveillance and chromosome ends are inappropriately processed by DNA repair pathways. Promotes binding of POT1 to single-stranded telomeric DNA. Modulates the inhibitory effects of POT1 on telomere elongation. The ACD-POT1 heterodimer enhances telomere elongation by recruiting telomerase to telomeres and increasing its processivity. May play a role in organogenesis.
Synonyms: PIP1; PTOP; TINT1; TPP1; DKCA6; DKCB7
Tractability: PROTAC: UniProt records ubiquitination sites on it; ubiquitination databases record sites on it; its protein half-life has been measured.
Gene: Protein-coding gene on chromosome 16 (67,657,512 to 67,660,810, reverse strand). Ensembl gene ENSG00000102977.
Subcellular location: Nucleus; Chromosome, telomere
Subcellular location (Human Protein Atlas): Nuclear bodies
Pathways (Reactome):
Cell Cycle: Inhibition of DNA recombination at telomere; Packaging Of Telomere Ends; Polymerase switching on the C-strand of the telomere; Processive synthesis on the C-strand of the telomere; Removal of the Flap Intermediate from the C-strand; Telomere C-strand (Lagging Strand) Synthesis; Telomere C-strand synthesis initiation; Telomere Extension By Telomerase
DNA Repair: Cleavage of the damaged purine; Cleavage of the damaged pyrimidine; Recognition and association of DNA glycosylase with site containing an affected purine; Recognition and association of DNA glycosylase with site containing an affected pyrimidine
Cellular responses to stimuli: DNA Damage/Telomere Stress Induced Senescence
Reproduction: Meiotic synapsis
Gene Ontology:
Molecular function: DNA polymerase binding; protein binding; protein-containing complex binding; telomerase inhibitor activity; telomeric DNA binding
Biological process: establishment of protein localization to telomere; intracellular protein transport; negative regulation of telomere maintenance via telomerase; protein localization to chromosome, telomeric region; regulation of establishment of protein localization to telomere; telomere assembly; telomere capping; telomere maintenance; telomere maintenance via telomerase; positive regulation of telomere maintenance; protection from non-homologous end joining at telomere
Cellular component: chromosome, telomeric region; nuclear body; nuclear telomere cap complex; nucleus; shelterin complex; nucleoplasm; telomerase holoenzyme complex
Genetic constraint (gnomAD): Loss-of-function variants: 40 observed, 56.55 expected, observed/expected ratio (o/e) 0.71, 90% interval 0.55 to 0.92. The upper end of that interval is the gene's LOEUF score, 0.92, which puts it in group 3 of 6, group 1 being the genes least tolerant of losing a copy. Missense variants: 526 observed, 597.34 expected, observed/expected ratio (o/e) 0.88, 90% interval 0.82 to 0.95. Synonymous variants: 273 observed, 255.14 expected, observed/expected ratio (o/e) 1.07, 90% interval 0.97 to 1.18.
Gene-disease validity (ClinGen):
ClinGen rates the evidence that ACD causes each of these diseases.
ACD-related short telomere syndrome (semidominant): Definitive. A spectrum of conditions, including dyskeratosis congenita, Hoyeraal-Hreidarsson syndrome, hereditary aplastic anemia, and pulmonary fibrosis, typically characterized by shortened telomeres due to a pathogenic variant(s) in ACD that results in impaired telomere maintenance.
Homologues: Orthologues: chimpanzee ACD (99% identical), macaque ACD (95% identical), dog ACD (77% identical), pig ACD (74% identical), guinea pig ACD (64% identical), rat Acd (60% identical), mouse Acd (59% identical), tropical clawed frog acd (22% identical), zebrafish acd (14% identical).
Diseases named in the same sentence as ACD in open-access papers:
ACD is named in the same sentence as 22 diseases in open-access papers, as found by Europe PMC text mining. Sharing a sentence is not in itself a finding about the gene and the disease. The quoted sentences say what the papers report.
melanoma (23 papers, 2015 to 2025). A malignant, usually aggressive tumor composed of atypical, neoplastic melanocytes. "We first looked at an extended list of high-risk genes predisposing to melanoma (ACD, CDKN2A, CDK4, POT1, TERF2IP, and TERT) or RCC (CDKN2B, FH, FLCN, MET, PBRM1, PTEN, SDHs, TSCs, and VHL) or both (BAP1 and MITF)." (PMID 34067022, 2021). "One patient carried the c.755delA (p.D255Afs*9) mutation in ACD (NM_001082486), another shelterin complex gene associated with high melanoma risk." (PMID 33050356, 2020). "ACD loss of function (LOF) mutations predispose to melanoma and a broader spectrum of cancers." (PMID 34067022, 2021). "Seven ACD and three TERF2IP pathogenic/likely pathogenic variants were totally identified supporting the pivotal role of telomere dysregulation in melanoma susceptibility." (PMID 40869905, 2025). "Multigene panel testing, including genes like CDKN2A, CDK4, BAP1, POT1, ACD, and TERF2IP, enhances the detection of hereditary melanoma risk." (PMID 39941357, 2025). "We also identified spitzoid morphology in melanomas from individuals with variants in TMG other than POT1 (TERF2IP, ACD, and TERT)." (PMID 36876055, 2023). "Spitzoid morphology was observed in 77% (23 of 30), 75% (3 of 4), 50% (2 of 4), and 50% (1 of 2) of melanomas from individuals with germline variants in POT1, TERF2IP, ACD, and TERT, respectively." (PMID 36876055, 2023). "•Spitzoid morphology is common in familial melanoma cases from individuals with POT1, TERF2IP, ACD, and TERT germline variants." (PMID 36876055, 2023). "In the case of sporadic melanomas, comprising more than 90% of all melanomas, several susceptibility loci acting as moderate (BAP1, TERT, POT1, ACD, TERF2IP and MITF) or low penetration genes have been identified." (PMID 36765773, 2023). "Telomere maintenance genes such as TERT, ACD, POT1 and TERF2IP were associated to melanoma predisposition previously." (PMID 35085295, 2022). "The main germline ACD and TERF2IP mutations are nonsense mutations associated with increased risk of multiple primary melanomas and earlier age of melanoma diagnosis, with a peak in the second decade." (PMID 34442055, 2021). "The overall contribution of recently identified CM predisposition genes (ACD, BAP1, POT1, MITF, and TERF2IP) to melanoma’s missing heritability is estimated to be about 2%." (PMID 32325837, 2020). "A total of 9 patients (3.4%) carried mutations in high-to-moderate melanoma risk genes (CDKN2A, POT1, ACD) and 22 (8.3%) patients in other cancer syndrome genes (NBN, BRCA1/2, CHEK2, ATM, WRN, RB1)." (PMID 33050356, 2020). "The purpose of this study was to perform a mutational analysis of the seven candidate melanoma susceptibility genes (ACD, BAP1, MC1R, MITF, POT1, TERF2IP, and TERT) in high-risk melanoma patients (familial melanoma and MPM) from southeastern Brazil, besides the CDKN2A and CDK4 genes." (PMID 37958811, 2023). "Spitzoid morphology involving at least 25% of the tumor was observed by at least 3 dermatopathologists in 77% (23 of 30), 75% (3 of 4), 50% (2 of 4), and 50% (1 of 2) of melanomas from individuals with germline variants in POT1, TERF2IP, ACD, and TERT, respectively." (PMID 36876055, 2023). "Four dermatopathologists reviewed the histology of melanomas from individuals with germline variants in POT1 (n = 30 melanomas, 17 individuals), TERF2IP (n = 4 melanomas, 3 individuals), ACD (n = 4 melanomas, 2 individuals), and TERT (n = 2 melanomas, 2 individuals)." (PMID 36876055, 2023). "POT1, ACD, and TERF2IP are members of the Shelterin protein complex, crucial for the safeguard of telomeres, and have been also described to be mutated in familial melanoma patients." (PMID 34123788, 2021). "We concluded that although the p.P116L isoform can localize to telomeric dsDNA through its interaction with ACD, it fails to bind telomeric ssDNA, which makes it a functionally deleterious mutation contributing to melanoma risk." (PMID 33050356, 2020).
melanoma (continued). "Increased genetic risk for melanoma can occur in the context of germline pathogenic variants in high-penetrance genes, such as CDKN2A and CDK4, risk variants in low- to moderate-penetrance genes (MC1R and MITF), and possibly due to variants in emerging genes, such as ACD, TERF2IP, and TERT." (PMID 37958811, 2023). "Furthermore, hereditary melanoma has been associated with germline mutations in high-risk melanoma susceptibility genes (CDKN2A, CDK4, TERT, POT1), polymorphisms in intermediate-risk melanoma susceptibility genes (BAP1, ACD, TERF2IP, MC1R and MITF), and germline missense substitutions in MITF." (PMID 32276436, 2020). "Other high-risk melanoma genes have been discovered: cyclin-dependent kinase 4 (CDK4), BRCA-1 associated protein (BAP1), and recently via exome sequencing of dense melanoma families, several new high-risk genes affecting telomere functions have been identified: POT1, ACD, TERF2IP and TERT." (PMID 25803691, 2015). "Recently, germline variants in genes involved in telomere regulation, including POT1, TERT, ACD, and TERF2IP, have been identified in melanoma-prone families." (PMID 40851494, 2025). "Our study findings support the inclusion of TMG (POT1, TERF2IP, ACD, and TERT) on genetic testing panels when a familial melanoma case exhibits spitzoid morphology in at least 25% of the tumor cells." (PMID 36876055, 2023). "Mutation in additional shelterin complex genes (adrenocortical dysplasia protein homolog, ACD; telomeric repeat-binding factor 2-interacting protein 1, TERF2IP) were found in familial melanoma patients." (PMID 31717496, 2019). "In particular, the protection of telomeres 1 (POT1) gene, adrenocortical dysplasia homolog (ACD) gene and telomeric repeat binding factor 2 interacting protein (TERF2IP) genes have been shown to be important in some melanoma families." (PMID 28097802, 2017). "Mutations have also been found in other members of the shelterin complex (ACD and TERF2IP) in melanoma families." (PMID 26433962, 2016). "Spitzoid morphology was also more prevalent in melanomas from individuals with TERF2IP, ACD, and TERT variants compared to noncarriers (OR = 82.4, 95% CI: 21.3-494.6; P < .001)." (PMID 36876055, 2023). "Therefore, panel testing for POT1, TERF2IP, ACD, and TERT should be considered when familial melanoma cases exhibit spitzoid differentiation." (PMID 36876055, 2023). "Compared to noncarriers (n = 139 melanomas), POT1 carriers (OR = 225.1, 95% confidence interval: 51.7-980.5; P < .001) and individuals with TERF2IP, ACD, and TERT variants (OR = 82.4, 95% confidence interval: 21.3-494.6; P < .001) had increased odds of spitzoid morphology." (PMID 36876055, 2023). "In a single melanoma patient with a negative family cancer history, we identified a mutation in the ACD gene truncating the C-terminal proportion of the protein containing POT1- and TINF2-interacting domains required for the localization of ACD protein into the shelterin complex." (PMID 33050356, 2020).
familial melanoma (5 papers, 2018 to 2025). Familial melanoma (FM) is a rare inherited form of melanoma characterized by development of histologically confirmed melanoma in two first degrees relatives or more relatives in an affected family. "While PVs have also been detected in several other genes, including CDK4, BAP1, ATM, MITF and multiple telomere stability genes TERT, POT1, ACD, and TERF21P, about half of the cases of familial melanoma remain unexplained." (PMID 40072281, 2025).
leukemia (3 papers, 2015 to 2023). A malignant (clonal) hematologic disorder, involving hematopoietic stem cells and characterized by the presence of primitive or atypical myeloid or lymphoid cells in the bone marrow and the blood. "Using a telomere restriction fragment assay, we also showed that this novel mutation in ACD leads to increased telomere length in leukemia cells." (PMID 26345285, 2015). "Cytotoxicity assays demonstrated a protective effect of the ACD p.G223V mutation against apoptosis in leukemia cells." (PMID 26345285, 2015). "Thus, we reduced the AcD concentration to avoid DNA damage and investigated the possible association of pTyr23AnxA2 with the promyelocytic leukaemia (PML) bodies." (PMID 26644180, 2016). "This study identified ACD as a novel gene involved in cALL and points to a functional role for ACD in enhancing leukemia cell survival." (PMID 26345285, 2015). "Despite the overexpression of wild-type, ACD does not lead to telomere lengthening, the G223V mutation reflects on TL and seems to be related to decreased apoptosis activity in B-ALL cells, that is triggered to the functional role of ACD and its relevance for cell survival in leukemia." (PMID 36980962, 2023). "Using in vitro assays, we showed that the private p.G223V mutation, adjacent to the TEL patch of the telomere protein ACD (also known as TPP1), leads to apoptosis resistance and may contribute to leukemia cell survival by promoting telomere maintenance and protection." (PMID 26345285, 2015).
B-acute lymphoblastic leukemia (1 paper, 2023). "Recently, NOTCH3, PAX5, CBFB, and particularly ACD were shown to drive the activated RAS pathway and monosomy 7 to B-acute lymphoblastic leukemia." (PMID 36980962, 2023).
brain cancer (1 paper, 2014). A primary or metastatic malignant neoplasm affecting the brain. "Furthermore, we highlight emerging evidence in support of the notion that defects in ACD in mammalian systems, which may play significant roles in the series of pathogenic events leading to the development of brain cancers." (PMID 24965943, 2014).
female infertility (1 paper, 2019). Diminished or absent ability of a female to achieve conception. "In this study we focus on the ACD+/− genotype, which shows a highly penetrant female infertility, yet the mice are quite healthy, without the severe kidney malformations associated with removal of additional Hox10,11 genes." (PMID 30872674, 2019).
Infertility (1 paper, 2019). "In this study we identify novel female fertility function for the Hoxc9,10,11 genes, with ACD+/− mice showing a much more severe infertility phenotype than AD+/− mice." (PMID 30872674, 2019). "The strongly synergistic phenotype, with Hoxc9,10,11 female mice showing normal fertility, and AD+/− females showing approximate 50% reduced fertility, while ACD+/− mice show complete infertility, certainly argues in favor of redundancy." (PMID 30872674, 2019).
monoclonal gammopathy of undetermined significance (1 paper, 2023). "An increase in expression of POT1, RAP1, TIN2, and ACD has been observed in MM cases than monoclonal gammopathy of undetermined significance (MGUS), predicting telomere role and as prognostic markers." (PMID 37131110, 2023).
cancer (9 papers, 2014 to 2025). A tumor composed of atypical neoplastic, often pleomorphic cells that invade other tissues. "ACD protein is a shelterin protein involved in the maintenance of telomere length and in cancer radioresistance, whereas telomeres have been reported to be regulated by many mechanisms, including phase separation-dependent mechanisms." (PMID 41154723, 2025). "The remaining three patient-specific mutations (ACD p.G223V, DOT1L p.V114F, HCFC1 p.Y103H) were novel mutations previously undescribed in public cancer databases." (PMID 26345285, 2015). "We found telomere maintaining genes (TERF2, CTC1, and ACD), genes involved in zinc homeostasis (MTF1 and SLC30A9), transcription elongation factor complex components (ICE1, ICE2, ELL), and BCL6 corepressors (BCOR, BCORL1) uniquely invoked in TNBC cancers." (PMID 40700427, 2025).
infection (2 papers, 2017 to 2019). The state of being infected such as from the introduction of a foreign agent such as serum, vaccine, antigenic substance or organism. "It has also been shown that Arabidopsis ACD mutant plants displayed excessive cell death upon infection with bacterial P. syringae." (PMID 30875866, 2019). "In contrast, ACD and Never ripe (Nr) mutants, in which ET biosynthesis and perception, respectively, are impaired, showed decreased disease symptoms and reduced fungal colonization on infection." (PMID 28390170, 2017).
tumor (2 papers, 2014 to 2023). "Interestingly, when larval brain tissue, mutant for genes encoding ACD regulators (e.g., aur-A, lgl and mira) or cell fate determinants (brat, numb and pros), is implanted into the abdomen of adult wild-type hosts, tumour formation ensue." (PMID 24965943, 2014). "Although the components of the ACD machinery, polarity proteins and polarized cell fate determinants are highly conserved in evolution, it remains largely unknown how significant a role ACD plays in human tumour formation." (PMID 24965943, 2014).
ACD also shares sentences with these, for which no sentence is quoted: breast carcinoma (2 papers); cutaneous melanoma (2); pulmonary fibrosis (2); acute myeloid leukemia (1); central nervous system disease (1); dyskeratosis congenita (1); haematological disorders (1); nephritis (1); ovarian carcinoma (1); Stroke (1); tauopathy (1).